KRAS (KRas proto-oncogene, GTPase)
Diseases named in the same sentence as KRAS in open-access papers (continued):
Sharing a sentence is not in itself a finding about the gene and the disease.
lung adenocarcinoma (continued). "Thus, it was possible to detect IDH mutation status and PTEN mutation status in gliomas, KRAS status in patients with colorectal carcinoma, and EGFR status in lung adenocarcinoma." (PMID 35884409, 2022). "For decades, KRAS mutant lung adenocarcinomas (LUAD) have been refractory to therapeutic strategies based on personalized medicine owing to the complexity of designing inhibitors to selectively target KRAS and downstream targets with acceptable toxicities." (PMID 34951114, 2022). "Last, our work is the first to show that Ampk can have a pro-tumorigenic role in Lkb1 mutant cancer in vivo, and suggests that KRAS/LKB1 mutant lung adenocarcinoma patients may benefit from CAMKK inhibitors." (PMID 33514834, 2021). "In addition, this work confirms the unique role of zygosity as an important modulator of response to treatment in patients affected by KRAS mutant lung adenocarcinomas." (PMID 34573384, 2021). "The TRU-type is a lung adenocarcinoma with bronchial epithelial phenotype with initial oncogene mutations such as EGFR, KRAS, and MET amplification, HER2 amplification, and later a second mutation leading to the loss of the BRM protein causing a subsequent poorer differentiation of the tumor." (PMID 34440689, 2021). "Moreover, multivariate survival analysis showed that SDPR expression and stage were independent predictors of prognosis in lung adenocarcinoma patients as well as in KRAS-mutant group." (PMID 33435990, 2021). "While our data support the hypothesis that retention of the WT copy of the KRAS gene in mutant lung adenocarcinomas modulates signaling events and response to treatment, a few study limitations must be addressed." (PMID 34573384, 2021). "As is already known, KRAS is a key oncogenic driver in lung adenocarcinomas, which is frequently observed in ever smokers and it is associated with a high TMB; hence, a subset of cases which carry other mutations may show a better response to ICI therapy." (PMID 34440689, 2021). "Thus, we screened a series of miRNAs with potential combination sequence with SDPR-related TFs, and constructed a competing endogenous RNA (ceRNA) network of SDPR in KRAS-mutant lung adenocarcinoma." (PMID 33435990, 2021). "For example, a recent paper by Liu and colleagues suggested that loss of the WT copy of the KRAS allele is not a rare event in lung adenocarcinomas and is associated with shorter survival." (PMID 34573384, 2021). "MYC and KRAS act as downstream conduits for other oncogenic drivers, enhancing the process of tumourigenesis in lung adenomas and their transformation to invasive and proliferative adenocarcinoma of the lung." (PMID 34445233, 2021). "In one case, a patient with lung adenocarcinoma with an external report of KRAS p.G12S." (PMID 34145282, 2021). "KRAS is the most frequently mutated oncogene in cancers, with mutation rates of up to 96% in pancreatic cancers, 54% in colorectal cancers (CRC), and 39% in lung adenocarcinomas." (PMID 33632153, 2021). "EGFR, ALK, and KRAS were common driver gene in Chinese patients with stage IV lung adenocarcinoma." (PMID 33997043, 2021). "Inhibition of ACK1 reduced the migration and invasion of KRAS mutant lung adenocarcinoma." (PMID 33495411, 2021). "Higher expression of IL22R1 has been reported in patients having KRAS-mutant lung adenocarcinoma." (PMID 35153741, 2021).
lung adenocarcinoma (continued). "In order to evaluate the presence and the proportion of CSCs, ALDH enzymatic activity was assessed using the ALDEFLUOR assay in three lung adenocarcinoma cell lines with different KRAS and EGFR mutational status: two KRAS mutant cell lines (A549 and H1734) and one EGFR mutant cell line H1975." (PMID 34127680, 2021). "We earlier reported a distinct frequency of 23% EGFR mutations and 18% KRAS mutations in lung adenocarcinoma patients of Indian ethnicity compared to 10–15% vs. 27–62% EGFR mutations and 25–50% vs. 5–15% KRAS mutations among the Caucasians and East Asians populations." (PMID 33796225, 2021). "In addition to EGFR, ALK-EML4 fusion, KRAS mutation, HER2 amplification, and PIK3CA mutation were also found in lung adenocarcinomas with MLCs." (PMID 34234879, 2021). "KRAS is a key oncogenic driver in lung adenocarcinoma (LUAD)." (PMID 33107184, 2021). "lams reported that transformation to SCLC could be a mechanism of resistance to nivolumab in KRAS-mutant lung adenocarcinoma." (PMID 34094904, 2021). "Because mutations in oncogenes such as EGFR and KRAS have been shown to occur in lung adenocarcinoma, the presence of KRAS and EGFR mutations in CMPTs has been hypothesized to be associated with lung adenocarcinoma by some investigators." (PMID 33960670, 2021). "The need for rigorous and accurate characterization of STK11 functional status is now urgent as clinical decisions governing the use of anti-PD-1 monoclonal antibody therapy for patients with KRAS-driven lung adenocarcinoma have come to depend upon accurate STK11 functional evaluation." (PMID 34849607, 2021). "Future studies should focus on whether similar adaptations drive tumor growth and survival in KRAS/LKB1 mutant lung adenocarcinoma." (PMID 33514834, 2021). "On the other hand, genetic studies involving multi-region sequencing of tumors have clearly shown that genetic heterogeneity exists in lung adenocarcinoma and EGFR mutations generally occur in the genetic trunk of the tumor and are hence clonal, whereas KRAS mutations are often sub-clonal." (PMID 33520716, 2020). "This suggests a tumor-promoting function of PIERCE1 in KRAS-mutant lung adenocarcinomas." (PMID 32728173, 2020). "Many of those adenocarcinomas of the lung are driven by the KRAS gene." (PMID 33126649, 2020). "This suggests that meth-HOXA9 may be found more commonly in advanced lung adenocarcinomas than mut-KRAS." (PMID 33322500, 2020). "KRAS is a strong initiator of tumorigenesis in lung adenocarcinoma." (PMID 32206449, 2020). "Despite the high frequency of somatic KRAS mutations in pancreatic and lung adenocarcinoma, we did not observe histologic abnormalities in either tissue (data not shown)." (PMID 32990679, 2020). "Here we aimed to test whether a combined blockade of Id1 and PD-1 is able to improve outcomes of mice models with KRAS-driven lung adenocarcinoma." (PMID 33126649, 2020). "Furthermore, it has been demonstrated that concomitant mutations in KRAS and STK11 confer poor survival in lung adenocarcinoma patients but their role in response to different kinds of treatments, including immunotherapy, need to be further elucidated." (PMID 32365882, 2020). "In vivo experiments in KRAS-mutant syngeneic and metastatic murine lung adenocarcinoma models showed that the combined blockade targeting Id1 and PD-1 was more effective than each treatment alone in terms of tumor growth impairment and overall survival improvement." (PMID 33126649, 2020).
lung adenocarcinoma (continued). "In line with this evidence is the inverse association between KRAS and PTEN in lung adenocarcinoma." (PMID 32793596, 2020). "However, vorinostat, in combination with gefitinib, showed synergistic cytotoxicity in lung adenocarcinoma and hepatocarcinoma with mutant KRAS." (PMID 32422889, 2020). "Indeed, epidemiological statistics indicate that EGFR and KRAS mutations are present in ~ 50% of lung adenocarcinomas, of which ~ 20% are EGFR mutations and 26% KRAS mutations." (PMID 33060649, 2020). "Interestingly, we can see the opposite effects on lung adenocarcinomas; KRAS mutant lung adenocarcinoma cell lines are more sensitive to N-bisphosphonates (p = 0.136) and to FTis (p = 0.007) than wild-type cells." (PMID 32524209, 2020). "Mutation or loss of STK11 is associated with low or absent PD-L1 expression, in both KRAS-mutant and KRAS-wild type lung adenocarcinoma, and with impaired efficacy of ICIs targeting the PD-1/PD-L1 axis." (PMID 33114576, 2020). "Based on these data, it appears that the depletion of SNORD50A/B often found in patient tumor samples is a key step for lung tumor initiation by activating the oncogenic KRas pathway, the genomic alterations of which represent about 25% of lung adenocarcinomas." (PMID 32111002, 2020). "Blockade of PD‐1/PD‐L1 pathway may be a promising therapeutic strategy for KRAS‐mutant lung adenocarcinoma." (PMID 33022831, 2020). "Although KRAS is the gene most frequently mutated in lung adenocarcinoma, an effective KRAS-targeted therapy has not yet been developed." (PMID 32481524, 2020). "Furthermore, in KRAS-mutant lung adenocarcinoma, combined inhibition of DDR1 and Notch signaling resulted in regression of patient-derived xenografts with an efficacy comparable to standard chemotherapy." (PMID 32211044, 2020). "Taken a glance in the BENEFIT study, the lung adenocarcinoma patients with concurrent mutations in EGFR and other oncogenes, including KRAS, had significantly shorter PFS than those with EGFR mutations only (13.2 months VS 4·7 months, HR 2.66, 95% CI 1.58–4.49; p = 0.0003)." (PMID 32505185, 2020). "Mutations in cancers other than HCC associated with a negative outcome for ICI treatment include inactivating mutations in JAK1/2 or beta-2-microglobulin in melanoma, MDM4 amplifications, or EGFR alterations in different stage IV tumors or STK11/LKB1 alterations in KRAS-mutant lung adenocarcinoma." (PMID 33353145, 2020). "Conversely, patients with KRAS mutations have a poorer prognosis than those without KRAS mutations, which is consistent with previous studies conducted on unselected lung adenocarcinoma." (PMID 33505917, 2020). "Expression of REG4 was significantly upregulated in a mutant KRAS-dependent manner in both colorectal stem cells and cancer tissues harboring APC mutation, consistent with another study with REG4 overexpression in KRAS mutant lung adenocarcinoma." (PMID 33489872, 2020). "Therefore, we aimed to retrospectively explore potential differences in DESCT features between KRAS and EGFR mutations in a cohort of Chinese patients with lung adenocarcinomas." (PMID 31783917, 2019). "Our data also suggest that, pharmacological targeting of this kinase may serve as a viable strategy for the treatment of human KRAS-mutant lung adenocarcinoma malignancy." (PMID 31001473, 2019). "The mucus produced in KRAS mutation lung adenocarcinoma and the rich blood supply of EGFR mutation lung adenocarcinoma may result in the lower quantitative value with KRAS mutations compared to EGFR mutations." (PMID 31783917, 2019).
lung adenocarcinoma (continued). "In lung adenocarcinomas, it is estimated that 25%–30% of patients harbor activating KRAS mutations, which have lower survival rates than those without KRAS mutations." (PMID 31484165, 2019). "This is not surprising as KRAS is the most frequently mutated gene in the lung adenocarcinoma but less frequent in the lung squamous cell carcinoma." (PMID 31791231, 2019). "Co-mutation of KRAS with loss of KEAP1 (kelch like ECH associated protein 1) further extended the glycolytic phenotype, dependence on glutamine, and sensitivity to glutaminase inhibitors in lung adenocarcinoma models." (PMID 31681559, 2019). "A study including 60 lung adenocarcinomas, either refractory or sensitive to both gefitinib and erlotinib, indicated that KRAS mutations lead to a lack of sensitivity to these drugs." (PMID 31795465, 2019). "Finally, yet importantly, STK11/LKB1 alterations have been described as a major driver of primary resistance to PD-1 blockade in KRAS-mutant lung adenocarcinoma." (PMID 31612108, 2019). "In this study we show that genetic inhibition of SHOC2 suppresses tumour development and elongates overall survival in KRAS-driven Lung adenocarcinoma (LUAD) mouse models, as well as inhibiting tumorigenic growth in a subset of KRAS- and EGFR-mutant human cell lines." (PMID 31182717, 2019). "For instance, EGFR and KRAS genes are frequently mutated in lung adenocarcinomas but with no overlap in individual samples." (PMID 30422399, 2019). "Riely and colleagues enrolled 33 patients with stage IIIb/IV lung adenocarcinoma, of which 30 had a KRAS mutation, however, none of the patients raised a radiographic partial response (PR)." (PMID 29464099, 2018). "Alterations in EGFR, as well as in other genes such as KRAS mutations or ALK translocations, are frequent in lung adenocarcinoma; all these changes have been involved in the activation of signaling pathways critical in lung tumorigenesis, such as MAPK and PI3K/AKT pathways." (PMID 29731995, 2018). "Interestingly, analysis of IL8 in lung adenocarcinoma patients revealed a significant positive correlation between IL8 expression, KRAS mutation status, disease-free survival and overall survival." (PMID 29416719, 2018). "Importantly, KEAP1/KRAS-mutant lung adenocarcinomas are dependent upon increased glutaminolysis and are therapeutically sensitive to pharmacologic inhibition of glutaminase." (PMID 30060526, 2018). "CDK4 has been shown necessary for tumor progression in a KRAS-induced lung adenocarcinoma model." (PMID 29464099, 2018). "Our results suggest that increasing proportions of signature 4 mutations do not significantly impact on the likelihood of a lung adenocarcinoma acquiring specifically a KRAS p.G12D mutation." (PMID 30412573, 2018).
lung adenocarcinoma (continued). "The problem of identifying the cell of origin of KRasG12D-induced lung adenocarcinomas was re-explored in a recent study where a peculiar strategy was used to express the mutant KRAS oncogene at the level of two different cellular compartments of epithelial bronchioalveolar cells." (PMID 30060526, 2018). "In the TCGA primary tumor samples, pancreas adenocarcinoma (PAAD) is the most KRAS mutant cancer type (somatic mutation frequency 90.6% of 149 cases), followed by colorectal adenocarcinoma (COAD, 42.5% of 220 cases) and lung adenocarcinoma (LUAD, 32.6% of 230 cases)." (PMID 30406144, 2018). "In lung adenocarcinomas, we recapitulate the mutual exclusivity between KRAS and EGFR as well as the importance of TP5328, for which our model suggests that it is frequently co-mutated with both KRAS and others like MLL3, as well as KRAS and STK11 are frequently co-mutated." (PMID 30341300, 2018). "Finally, consistent with the previous NSCLC dataset, GATAD2B copy-number driven expression (****p < 0.0001, t-test) was higher in KRAS mutant compared to wild type lung adenocarcinomas (n = 517 patients, Wilcoxon rank-sum, p < 0.0350)." (PMID 30013058, 2018). "Murine KRAS mutant lung adenocarcinoma cell line, ADS-12, was established in house." (PMID 30400835, 2018). "Other mechanisms for the combinatorial effects of CDK4/6 and MEK inhibition in the KRAS-driven lung adenocarcinoma model may also be contributing, including an induction of senescence not observed after exposure to palbociclib alone." (PMID 30167080, 2018). "In our analysis, we noted a negative association between signature 4 and KRAS p.G12D (c.35G>A) in lung adenocarcinoma where P = 0.0075, which is just above our threshold for defining significance (P < 0.004)." (PMID 30412573, 2018). "Aberrant mutations in KRAS play a critical role in tumor initiation and progression, and are a negative prognosis factor in lung adenocarcinoma (LUAD)." (PMID 29504894, 2018). "KRAS p.G12D transition mutations are the most common KRAS somatic mutation arising in the lung adenocarcinomas of people who have never smoked." (PMID 30412573, 2018). "Interestingly, the mutational landscape of murine lung adenocarcinomas originated by carcinogens [methyl-nitrosourea (MNU) and urethane] or by genetic activation of KRAS (KRASLA2) was compared." (PMID 30060526, 2018). "Specific KRAS/NRAS mutations are correlated with differences in protein profiles for melanomas and thyroid cancer and also for testicular germ cell tumors, endometrial carcinoma, and lung adenocarcinoma (in conformity with OncoKB level 4 data)." (PMID 30442178, 2018). "Radiographically confirmed partial responses could be detected in an ampullary adenocarcinoma metastatic to the liver, in a KRAS-mutant lung adenocarcinoma and in cases of breast and gastroesophageal cancer." (PMID 28002805, 2017). "In lung adenocarcinoma, the presence of KRAS or the absence of targetable mutation are associated with PD-L1 expression, whereas EGFR or other common mutated adenocarcinoma rarely express PD-L1." (PMID 28671973, 2017). "We observed no strong positive correlations for lung adenocarcinoma, providing evidence that the transcriptional effects of mutations in KRAS, EGFR, MET, NTRK1, and PIK3CA are distinct from each other." (PMID 29322935, 2017). "In addition, our study is the first that showed metastatic site-specific variation of the prognostic value of KRAS status in lung adenocarcinoma." (PMID 28051122, 2017).